ULK1 (unc-51 like autophagy activating kinase 1)
Diseases named in the same sentence as ULK1 in open-access papers (continued):
Sharing a sentence is not in itself a finding about the gene and the disease.
cancer (continued). "ULK1 expression correlates with poor prognosis in nasopharyngeal, breast, colorectal and gastric cancers." (PMID 29233870, 2017). "qRT-PCR assay was again employed to test Ulk1 mRNA expression in the cancer cell lines, and its level was compared with that in GES-1 gastric mucosal epithelial cells (non-cancerous normal cells)." (PMID 28410240, 2017). "Among all the clinic features, high Ulk1 expression was significantly correlated with T classification (P=0.014) and cancer relapse (P=0.007)." (PMID 28410240, 2017). "Quantified blot results integrating total 12 tissue samples confirmed significant Ulk1 protein upregulation in cancer tissues." (PMID 28410240, 2017). "The IHC staining assay results showed that Ulk1 was mainly expressed in the cytoplasm of cancer cells." (PMID 28410240, 2017). "HF was documented to regulate Akt-mTORC1 signaling in CRC, and mTORC1 also inhibits autophagy through phosphorylation and inactivation of the initiating kinase ULK1 in cancer cells, prompting us to ask if and how HF regulates autophagy in CRC cells." (PMID 28492544, 2017). "Quantification results showed about 2-3 times higher of Ulk1 protein expression in cancer cells (vs. GES-1 epithelial cells)." (PMID 28410240, 2017). "Given that autophagy and hypoxia are implicated to play an important role in cancer, we further investigated miR-93-based regulation of ULK1, and hypoxia-mediated modulation of miR-93 in human cancer cells." (PMID 29109831, 2017). "The present study revealed that CuE suppressed mTORC1 activity as evidenced by the decreased phosphorylation of its direct substrates p70S6K and ULK1, concomitant with the induction of autophagy in human cancer cells." (PMID 25970614, 2015). "Rapamycin, which failed as a cancer monotherapy, acts proximal to the Becn1/Ulk1/Vps34 autophagy initiation complex by inhibiting mTORC1." (PMID 26418751, 2015). "In light of its dual function as promising prognostic biomarker as well as novel molecular target for cancer therapy, ULK1 had attracted substantial attention over the last several years." (PMID 25714809, 2015). "Furthermore, phosphorylation of ULK1 and its binding protein by cyclin-dependent kinase 1/cyclin B promotes mitotic entry and cell cycle progression, as indicated by impaired cancer growth upon genetic deletion of ULK1 or ATG1367." (PMID 41408407, 2025). "ULK-1 inhibition is therefore of great therapeutic interest for cancer." (PMID 40291494, 2025). "Additionally, phenothiazines promote mitophagy through the AMPK/mTOR/ULK1 pathway, enhancing autophagy and mitigating mitochondrial damage in cancer cells." (PMID 40718442, 2025). "Additionally, the experimental ULK1 inhibitor DCC-3116 has entered Phase 1 clinical trials to evaluate its potential in treating RAS-driven cancers, both as a monotherapy and in combination with MAPK inhibitors." (PMID 40001518, 2025). "However, despite the increasing interest in ULK1-targeted therapies, the exact role of ULK1 in cancer progression remains poorly understood." (PMID 41408407, 2025). "SBI-0206965, a 2-aminopyrimidine derivative, was originally identified through a cell-based screen and described as a selective inhibitor of the autophagy initiator kinase ULK1, with the ability to inhibit ULK signaling and ULK1-mediated survival of cancer cells." (PMID 40845097, 2025). "The molecular mechanisms underlying CLDN1-mediated cancer chemoresistance are diverse and include its interaction with EPHA2 kinase, which promotes stemness, the upregulation of Unc-51-like autophagy activating kinase 1 (ULK1) phosphorylation, and significant alterations in metabolic pathways." (PMID 40943068, 2025). "ULK1 plays a crucial role in cancer, neurodegenerative diseases and so on." (PMID 39215364, 2024). "Our findings suggests that CBZ may affect autophagy differently in cancers, or that the affect it has on ULK1 phosphorylation may be slightly counteracted by its effect on ULK1 mRNA levels." (PMID 38446332, 2024).
cancer (continued). "ULK1 plays a crucial role in regulating autophagy in cancer cells." (PMID 39650664, 2024). "ULK1 has been extensively documented in various human diseases, including cancer." (PMID 38286802, 2024). "Emerging evidence suggests that ULK1’s regulation could be crucial for overcoming drug resistance in various cancer types." (PMID 38240686, 2024). "Interestingly, upregulation of ULK1 has been observed in various cancers, including non-small cell lung cancer, colorectal cancer, nasopharyngeal carcinoma, and clear cell renal carcinoma." (PMID 37564206, 2023). "A growing number of ULK1 inhibitors have been researched and reported to suppress tumor growth and metastasis and promote autophagy in various cancer types, such as 3s158, SBI-0206965160, WP1130161, ULK-100162, ULK-101162, MRT67307163, MRT68921163, compound 3g164, and compound 6165." (PMID 37564206, 2023). "To address whether mitophagy induction by hypoxia/Lon augments cell survival in cancer cells, we determined the cell viability of cancer cells treated with the ULK1 inhibitor SBI-0206965 or lysosomal H + ATPase inhibitor bafilomycin A1 (BafA1)." (PMID 36927870, 2023). "In summary, these studies unveil ULK1 as a novel therapeutic target for HCC and indicate that targeting ULK1, in combination with other anti-cancer therapies, may be a promising interventional strategy for the treatment of HCC." (PMID 35252196, 2022). "In addition, high levels of copper in cancer cells activate ULK1 and two kinases that regulate autophagy pathway, which enables cancer cells to resist cell death." (PMID 36703728, 2022). "Overall, the inhibition of ULK1 seems to be a promising strategy for cancer therapy." (PMID 34830777, 2021). "Cancer cells with activating mutations in RAS have high levels of autophagy, necessary for metabolic maintenance and oncogenic transformation but inhibition of MEK has also been shown to activate the AMPK/ULK1 signaling axis and induce autophagy in RAS mutated cancers." (PMID 33763424, 2021). "Cytotoxic autophagy mediated by induction of ULK1 was shown in several cancer cells including PDAC." (PMID 34830816, 2021). "Mechanistically, CPT inactivates neddylation pathway, which induce the expression of p-IκBα to modulate AMPK/mTOR/ULK1 pathway to trigger pro-survival autophagy, whereas targeting this pathway blocks the autophagic response and thus sensitizes cancer cells to CPT-induced apoptosis." (PMID 33898327, 2021). "Elevated glycolysis resulting from aberrant amplification of PKM2 gene in cancer cells is accompanied by the onset of hypoxia sensing, which simultaneously instigates autophagic flux through activation of ULK1/2 34, 35, making the two catabolic events central step for tumorigenesis individually." (PMID 34345207, 2021). "Previous studies indicated that the activation of AMPK/ULK1 pathway induced autophagy, and inactivation of the mTOR pathway could promote autophagy in multiple human cancers." (PMID 33898327, 2021). "ATG2B, ATG2A, ULK1, and RB1CC1 had a wide range of mutation frequencies in the pan-cancer analysis." (PMID 34636718, 2021). "In recent years, ULK1 disorders have been found in several human cancers." (PMID 34539897, 2021). "In our study, we sought to determine whether selectively inhibiting NUAK1 and ULK1 could be an effective way to target oxidative stress homeostasis in cancer cells." (PMID 32873786, 2020). "Curcumin impairs the autophagic flux, as it acts as a specific chemosensitizer for cancer and, in association with 5-FU, decreases AMPK/ULK1-dependent autophagy, modulates AKT, and increases apoptosis, amplifying the antitumor effects of 5-FU in colon cancer cells and in human melanoma cells." (PMID 33233671, 2020). "ULK1 has been shown to promote cell survival in several cancers." (PMID 32393312, 2020).
cancer (continued). "We could therefore conclude that NEDD4L depletion in cancer cells facilitated ULK1-mediated autophagy and ASCT2-mediated glutamine uptake to supply appropriate fuel to activate mitochondrial metabolism and maintain mitochondrial functional integrity." (PMID 31959741, 2020). "Moreover, it regulated autophagy by repressing the phosphorylation of ULK1, which promotes cancer cell survival, proliferation, migration, and invasion, and p62, which leads conjugated proteins to degradation." (PMID 32182828, 2020). "Our studies suggested that targeting AMPK/ULK1 pathway may be a promising approach in the treatment of cancer." (PMID 31001120, 2019). "ULK1 was an initiate autophagy gene, and the down-regulation of ULK1 had been found in cancer." (PMID 32038722, 2019). "Recently more ULK inhibitors, such as ULK100 and ULK101, have been described, which supports that the idea that blocking ULK1 may be a good strategy for cancer therapy." (PMID 31635099, 2019). "Importantly, ULK1 modulators are emerging in the context of cancer research and it will be interesting to evaluate their potential in the context of protein-misfolding diseases." (PMID 30502498, 2019). "So far, apart from a single nucleotide polymorphism (SNP) in ULK1 that is associated with CD, other disease-associated mutations of the ULK1 complex have not been reported, though altered ULK1 expression has been associated with cancer." (PMID 29233870, 2017). "Indeed, one of these studies showed that dual inhibition of ULK1 and mTOR promoted cancer cell apoptotic death." (PMID 29233870, 2017). "As mTOR inhibition results in ULK1 and autophagy activation, this might give an advantage to cancer cells in order to survive drug treatment." (PMID 29233870, 2017). "Ulk1 mRNA level in cancer tissues was about four times higher than that in the normal tissues." (PMID 28410240, 2017). "mTORC1 activation would also inhibit autophagy by inhibiting Unc-51-like kinase 1 (ULK1) and the inhibition of mTORC1 could trigger autophagy and be used in cancer therapy." (PMID 28320471, 2017). "Additionally, we found that resveratrol induces death of the cancer cells known to be sensitive to mTOR inhibition in ULK1 dependent manner." (PMID 26902888, 2016). "We also found that resveratrol-induced cancer cell suppression occurred ULK1 dependently." (PMID 26902888, 2016). "Next, we examined whether ULK1 is involved in resveratrol-induced suppression of cancer cell viability." (PMID 26902888, 2016). "These cancer cell specific and ULK1 dependent effect of resveratrol further supports the idea that resveratrol-induced cellular behavior alterations occurred through mTOR-ULK1 pathway." (PMID 26902888, 2016). "We examined whether basal autophagy in these cancer cells may be driven by upregulated phosphatase activity for ULK1 while maintaining mTORC1 function intact." (PMID 26310906, 2015). "Furthermore, inhibition of glutaminase activity by the active alkyl benzoquinone AV-1 in carcinoma cells led to autophagy via AMPK-mediated ULK1 activation and mTORC1 inhibition, ultimately leading to inhibition of cancer cell growth." (PMID 25026281, 2014). "Moreover, the role of miR-25 in regulating autophagy via targeting ULK1 remains to be validated in other cancer models." (PMID 25026296, 2014). "Our findings reveal that miR-142-3p overexpression not only reduces ULK1 protein levels but downregulates lysosomal function-associated gene SLC17A5, and the autophagosome–lysosome attachment gene STX12, highlighting its potential to disrupt autophagy and lysosomal processes in cancer cells." (PMID 40362400, 2025). "Similarly, ULK1 plays a key role in the formation of pre autophagosome and promoting the occurrence of autophagy and has been found to be abnormally expressed in a variety of malignant tumors." (PMID 35692501, 2022).
cancer (continued). "Neferine induces autophagic cell death in a panel of cancer cells, including apoptosis-defective and -resistant cancer cells or isogenic cancer cells, via Ca2+ mobilization through the activation of ryanodine receptor and ULK1/PERK and AMPK/mTOR signaling cascades." (PMID 34575981, 2021). "Of note, PDAC therapy could further benefit from combination of small-molecule ULK1/2 kinase inhibitor and 2-DG or 3-BP, supporting investigation of autophagy blockade in combination with the two anti-cancer agents as a promising therapeutic approach in clinical trials of PDAC patients." (PMID 34345207, 2021). "As known, ULK1 is a protein that participates in the initiation of autophagy and its downregulation via microRNAs could inhibit autophagy progression in many types of cancers." (PMID 33572255, 2021). "Interestingly, the total levels of ULK1 were similar in pancreatic normal and cancer cell lines." (PMID 33654220, 2021). "Therefore, we predict that dual inhibition of NUAK1 and ULK1 could induce a significant synergistic cytotoxic effect on various cancer types." (PMID 32873786, 2020). "The findings that high levels of ULK1 are associated with poor prognosis in several solid tumors and that ULK1 inhibition can rescue the phenotype induced by caspase-3 deletion in AML1/ETO AML cells suggest that ULK1 is a promising new therapeutic target for cancers." (PMID 32393312, 2020). "ULK1 may play a pivotal role in cancer by promoting cell death." (PMID 32038722, 2019). "Consequently, Ulk1 protein expression was also increased in cancer cells." (PMID 28410240, 2017). "Therefore, we examined whether resveratrol-induced suppression of cancer progression occurred through mTOR and inhibition of ULK1." (PMID 26902888, 2016). "Thus, ULK1 is an attractive biomarker for autophagy that could be used in many diseases, especially cancer." (PMID 25714809, 2015). "Furthermore, inhibitor of ULK1 could be emerged as a novel promising cancer therapeutic strategy by compromising autophagic cell survival." (PMID 25714809, 2015). "Our findings indicate that DAZAP1 reduces ULK1 decay, thereby activating mitophagy and enhancing OXPHOS to fulfill the metabolic demands of cancer stem cells." (PMID 40401521, 2025). "Here, we investigate how ULK1 function influences PDAC progression by using syngeneic orthotopic and spontaneous cancer GEM models." (PMID 41408407, 2025). "Even though several autophagy regulators like mTOR, ULK1, and AMPK have been identified, Beclin-1 is considered a crucial controller of autophagy in cancer." (PMID 39650649, 2024). "Therefore, trying to regulate autophagy using existing ULK1 inhibitors that have been applied to other kinds of cancers or developing new ULK1 inhibitors is a promising direction for EC therapeutic research and may have far-reaching ramifications in the future." (PMID 37564206, 2023). "Notably, Deciphera’s ULK1/2 inhibitor, DCC-3116, is in clinical trial with RAS/MAPK pathway mutation (ClinicalTrials.gov, NCT04892017, accessed on 20 December 2022), because treatment of RAS mutant cancer cells with MAPK pathway inhibitors increases autophagy for cancer cell survival." (PMID 36674464, 2023). "The activation of ULK1 and ULK2 by Cu enhances energy production in cancer cells, which sustains the energetic cost of continuous cell growth and division." (PMID 36430490, 2022). "The ability of Cu to facilitate cellular respiration through COX function and promotion of autophagy through ULK1 and ULK2 activation enhances cancer cell survival." (PMID 36430490, 2022).
cancer (continued). "ULK1 is a key regulator of autophagy, which plays a role in the regulation of drug resistance in NSCLC cells and cancer progression, suggesting that HOTAIR is a novel target for NSCLC therapy." (PMID 35379783, 2022). "More specific autophagy modulators, such as ULK-1 inhibitors and selective inhibitors of VPS34, a Class III PI3K, are also effective inhibiters of autophagy and in development as cancer therapy." (PMID 35608088, 2022). "More specific autophagy inhibitors are in development, including the ULK-1 inhibitors SBI-0206965 and MRT68921, which are in development as cancer therapies." (PMID 35608088, 2022). "UNC-51-like kinase 1 (ULK1) and Beclin1 that play a vital role at initiated step of autophagy have been reported in the treatment of cancer." (PMID 33907539, 2021). "Consistent with our cell biological study that shows favorable effect of esomeprazole in controlling cancer cell growth, the RPPA data revealed that esomeprazole regulates critical cell cycle proteins such as p21, p300, cyclin C, and ULK1." (PMID 34262645, 2021). "Similar to ULK1, ATG101 in the same complex for autophagy initiation, the protein levels were gradually reduced in MIA PaCa-2 and HeLa cancer cell lines by treatment with the protein synthesis inhibitor cycloheximide (CHX)." (PMID 34502089, 2021). "Another key activator of autophagy in cancer cells is the energy sensor kinase AMPK, which phosphorylates ULK1 on Ser555, similar to ESCs." (PMID 34832087, 2021). "In summary, our study has demonstrated a new therapeutic strategy for inhibiting cancer growth with dual-targeting antioxidant mechanisms and mitophagy using a NUAK1/ULK1 dual inhibitor, MRT68921." (PMID 32873786, 2020). "Taken together, the current data demonstrate that ceRNAs can participate in many steps of autophagy by upregulating some key molecules, such as ULK1, ATG3, ATG7, and ATG4, resulting in chemoresistance in various cancers." (PMID 33050642, 2020). "HOTAIRM1 functions as a ceRNA to regulate autophagy initiation and elongation through ULK1, ATG3, ATG7, and ATG12 in cancers." (PMID 33050642, 2020). "Lc3b mRNA (p < 0.05) was increased by cancer whereas the protein content of LC3I, p-ULK1Ser757 as well as total ULK1 and Bcl-2 and p62 mRNA were unaltered." (PMID 30713500, 2018). "All three genes are induced in hypoxic conditions via PERK/ATF4 and their knockdown, or knockdown of PERK and/or ATF4, reduces cancer cell proliferation (TRIB3 and ULK1), survival (ULK1), and migration (LAMP3) in hypoxia." (PMID 30248920, 2018). "While the development of ULK-1/2 small molecule inhibitors is underway, the data on the prognostic value of ULK-1/2 in different cancers is scarce and contradictory." (PMID 28696368, 2017). "Additional studies in larger patient cohorts are required to better define the prognostic values of ULK1 and ULK2 in different cancer types." (PMID 28696368, 2017). "Scatter plot of genes array data showed that LP-4 up-regulated the Igf1, Fam176a, Ulk-1, PERK, Cxcr4, and Sqstm1 (p62) genes in HeLa cancer cells." (PMID 28670281, 2017). "In this research, we have found that the genes engaged in the induction of autophagy ULK1 and UVRAG have the lowest expression levels in both cancer and normal tissue." (PMID 28035578, 2017). "The strong correlation between PTEN and ULK1 warrants a further study of PTEN in autophagy and cancer." (PMID 25909167, 2015). "The mTOR/Raptor pathway is thought to suppress ULK1 and ULK2 and their regulatory subunits, while AMPK phosphorylates ULK1, leading to autophagy-mediated cancer cell death." (PMID 23875169, 2013). "Therefore, further investigation of the interaction and phosphorylation regulation between ULK1 and AMPK will facilitate our knowledge on the mechanisms of the AMPK-ULK1-mTORC1 complex in autophagy induction and autophagy-associated diseases including cancer and neurodegeneration." (PMID 21072212, 2010).